AZIN1 (antizyme inhibitor 1)
Diseases named in the same sentence as AZIN1 in open-access papers (continued):
Sharing a sentence is not in itself a finding about the gene and the disease.
tumor (39 papers, 2014 to 2025). "This is consistent with prior research that has linked AZIN1 alterations to more aggressive tumor morphologies in other malignancies, but the explicit relationship to angiogenesis through IL-8 has not been thoroughly investigated until now." (PMID 40852728, 2025). "Recent evidence from clinicopathological analyses has strengthened the signature by correlating elevated RNA-editing level of AZIN1 with the risk of liver cirrhosis, tumor recurrence, and worse prognosis." (PMID 38169396, 2024). "In patients, both editing and nuclear localization of AZIN1 are common and are associated with tumor aggressiveness, i.e., a higher Gleason score, higher genomic instability, and a shorter progression-free survival time." (PMID 36202978, 2022). "This is the first time that both the presence of AZIN1 and its nuclear localization have been associated with increased tumor aggressiveness and clarifies that this association is due to high RNA editing." (PMID 36202978, 2022). "Recent reports show that A-to-I editing of AZIN1 is intimately associated with augmented tumor-initiating potential and tumor-aggressive behavior." (PMID 35365616, 2022). "Blocking these interactions prevented nuclear accumulation of AZIN1 as well as the acquisition of cellular phenotypes associated with increased tumor aggressiveness." (PMID 36202978, 2022). "Increasing the level of AZIN1 within the cells has a significant promoting effect on tumour growth and has been associated to kidney fibrosis." (PMID 32752173, 2020). "This resulted in hyper-editing of AZIN1, which conferred a gain-of-function phenotype associated with a more aggressive tumor behavior." (PMID 30304856, 2018). "AZIN1 overexpression leads to a more aggressive tumor phenotype by binding to – and inhibiting – its target, antizyme." (PMID 39962590, 2025). "Measuring the tumor size at progressive time points, we found that knockout of AZIN1 resulted in significantly slower tumor growth." (PMID 39962590, 2025). "Given our prior data demonstrating that AZIN1 overexpression increases cell invasive capacity, we measured tumor dissemination by studying brain sections of mice 14 days after intracranial injection." (PMID 39962590, 2025). "In a proof-of-principle study, we found decreased AZIN1 levels in the urine of two patients undergoing surgical removal of the tumor." (PMID 39962590, 2025). "AZIN1 overexpression can induce a more aggressive tumor phenotype via increased binding and resultant inhibition of antizyme." (PMID 39962590, 2025). "AZIN1 is secreted in patients with MB and its measured levels of urinary and CSF AZIN1 correlate with tumor status." (PMID 39962590, 2025). "In summary, these in vivo studies revealed that the AZIN1 KO group had reduced tumor progression and prolonged survival, demonstrating that AZIN1 has a role in MB growth and dissemination." (PMID 39962590, 2025). "Since drawing CSF from patients is considered to be an invasive procedure, as a proof of concept, we quantified AZIN1 in the pre-and post-tumor resection surgery urine samples of two MB patients (with MYC amplification status)." (PMID 39962590, 2025). "The combination of ADAR1 with AZIN1 knockdown enhanced these effects, while in vivo experiments validated decreased tumor growth and AZIN1 expression." (PMID 40852728, 2025). "A-to-I editing of AZIN1 enhances c-Myc stabilization and IL–8-mediated angiogenesis, establishing a permissive vascular niche for tumor progression." (PMID 40852728, 2025). "Further supporting these findings, an orthotopic tumor model in mice revealed that AZIN1 knockdown markedly inhibited tumor growth in vivo." (PMID 40246846, 2025). "Conducting in vivo studies we found that knocking-out AZIN1 in tumors corresponds with reduced tumor progression and prolonged survival." (PMID 39962590, 2025).
tumor (continued). "In CRC, ADAR1 enhances tumor progression through AZIN1 editing, stabilizing c-Myc and promoting IL-8–mediated angiogenesis, while also activating FAK/AKT signaling and inhibiting ferroptosis." (PMID 40852728, 2025). "For diagnosis, COPA A-to-I editing in CRC can predict immunotherapy response, while AZIN1 editing influences tumor angiogenesis via IL-8 regulation; elevated AZIN1 editing in GC serves as an independent risk factor for prognosis and lymph node metastasis." (PMID 41446042, 2025). "Limited nutrients and oxygen are often the feature of early avascular tumors and late-stage necrotic tissues, and high level of AZIN1 can confer growth advantage, thus aiding tumor formation." (PMID 38169396, 2024). "Taken together, AZIN1 seems to play an anti‐tumor role and serves as a favorable prognostic factor in KIRC." (PMID 39140420, 2024). "With the ssGSEA algorithm, we analyzed the tumor immune microenvironment of high and low AZIN1 groups in the TCGA cohort." (PMID 39140420, 2024). "On the other hand, transgenic mice with tissue-specific AZIN1 overexpression have increased tumor incidence, elevated level of polyamine, and triggered enhanced proliferation." (PMID 38169396, 2024). "Compared with wild type AZIN1, edited-AZIN1 obtains a stronger binding ability with AZs, promoting protein stability and tumor cell proliferation through inhibiting AZs-mediated degradation of ODC and cyclin D1." (PMID 38169396, 2024). "Tumor cells overexpressing AZIN1 exhibit higher sensitivity to polyamine analogs due to osmotic imbalance caused by the elevated cellular polyamine level." (PMID 38169396, 2024). "This study illustrated the unique anti‐tumor role of AZIN1 in KIRC and provided potential value for guiding immunotherapy and targeted therapy." (PMID 39140420, 2024). "Edited AZIN1, which is translocated into the nucleus, promotes cell proliferation and tumour progression through polyamine-dependent and -independent mechanisms." (PMID 37209819, 2023). "The functional effects of RNA-edited AZIN1 on tumor angiogenesis have been exhaustively studied recently." (PMID 37217462, 2023). "RNA-edited AZIN1 has been reported to increase tumor angiogenesis by upregulating IL-8 in vivo and in vitro." (PMID 37217462, 2023). "To investigate the functional impact of edited AZIN1 in tumor-induced angiogenesis, we introduced V5-tagged WT AZIN1 and mutant AZIN1_S367G cDNAs into HCT 116 and HT-29 cell lines." (PMID 35365616, 2022). "Regulation of c-Myc, a known transcriptional factor of IL-8, by RNA-edited AZIN1, is novel connection between the RNA-edited AZIN1 and tumor angiogenesis." (PMID 35365616, 2022). "In contrast to AZIN1 expression, the subcellular AZIN1 localization differed markedly between the tumor and benign control samples, with 98/202 tumor samples (49%) and 0/26 benign samples (0%; p < 0.001) exhibiting nuclear AZIN1 localization." (PMID 36202978, 2022). "The significant effect of edited AZIN1 on tumor vascular microenvironment provides a notable rationale for further exploring how to target tumor vasculature to achieve better treatment efficacy." (PMID 35365616, 2022). "Our study suggests an important contribution of RNA-edited AZIN1 to the tumor vascular microenvironment and highlights its translational potential." (PMID 35365616, 2022). "We showed here that RNA-edited AZIN1 promoted tumor angiogenesis through the upregulation of IL-8 via in vitro and in vivo experiments." (PMID 35365616, 2022). "Despite the growing evidence for A-to-I RNA editing in tumorigenesis, the functional role and the clinical significance of AZIN1 RNA editing in CRC tumor angiogenesis remains unexplored." (PMID 35365616, 2022). "Increased AZIN1 expression correlates with elevated polyamine levels, which promote tumor cell proliferation." (PMID 36119047, 2022).
tumor (continued). "Controlling for both the expression of the AZIN1 isoform and the myosin-mediated shuttling of edAZIN1 also allowed us to explore how nuclear localization of AZIN1 influences cellular behaviors that are known to predict tumor aggressiveness." (PMID 36202978, 2022). "The generation of conditional mouse models with wild type and edited AZIN1 genes would provide valuable information on the relationship between AZIN1 and AZIN1 editing with tumor development." (PMID 30304856, 2018). "Although AZIN1 editing was also detected in healthy liver tissues, the level of editing increased with the pathological behaviour of the tumor." (PMID 30304856, 2018). "The global mean editing frequency and the AZIN1 specific editing frequency were higher in tumor compared to matched-normal breast tissues." (PMID 26440892, 2015). "We also compared the specific edit frequency of the AZIN1 transcript determined by high-depth amplicon sequencing (Roche FLX sequencer) between tumor and matched normal breast tissues." (PMID 26440892, 2015). "Through next-generation RNA sequencing technology, an A-to-I editing event within the AZIN1 transcript was identified in the tumor tissues from HCC patients." (PMID 24916440, 2014). "Notably, the knockdown of AZIN1 effectively curtailed tumor growth and heightened the tumor’s sensitivity to immunotherapy." (PMID 40246846, 2025). "AZIN1 editing promotes tumor angiogenesis via IL-8 upregulation and c-Myc stabilization." (PMID 40852728, 2025). "In conclusion, this novel anti‐tumor role of AZIN1 in KIRC was identified in this study." (PMID 39140420, 2024). "Collectively, these reaffirmed that increased polyamines resulted in the opposite of the Warburg effect and inhibition of tumor cells, which might be the reason for the anti‐tumor role of AZIN1 in KIRC." (PMID 39140420, 2024). "AZIN1 promotes tumor angiogenesis in colorectal cancer by upregulating IL‐8, and the IL‐8 receptor profoundly affects the tumor microenvironment, increasing the proliferation, survival, and migration of vascular endothelial cells and the permeability of endothelial cells." (PMID 39006762, 2024). "Edited AZIN1 exhibits a gain-of-function phenotype involving aggressive tumor behaviors." (PMID 35365616, 2022). "Moreover, nude mice injected with cells expressing edited AZIN1 exhibited faster tumor growth and tumor angiogenesis." (PMID 35365616, 2022). "Studies have shown that AZIN1 can up-regulate IL-8 and promote tumor angiogenesis." (PMID 36119047, 2022). "Furthermore, and in accordance with our in vitro data, tumor vessel density was significantly increased in edited AZIN1-HCT 116 tumors compared to the control and WT AZIN1-HCT 116 groups, as determined by the micro-CT scans." (PMID 35365616, 2022). "Here, we first explored the role of edited AZIN1 in the tumor vascular microenvironment of CRC." (PMID 35365616, 2022). "In addition, the authors were able to successfully demonstrate that higher levels of edited AZIN1 promoted an increased incidence of tumor formation and invasive ability." (PMID 30197877, 2018). "Taken together, our data for the first time, suggest that measurement of AZIN1 RNA editing status could be a promising prognostic biomarker for tumor recurrence and survival in patients with GC." (PMID 30563560, 2018). "In addition, induced overexpression of AZIN1 stimulates the growth, survival and oncogenic potential of tumor and non-tumor cells." (PMID 30304856, 2018). "Interestingly, the current study clearly demonstrated that hyper-editing status of AZIN1 RNA in primary tumor tissues significantly correlated with the presence of LNM, while logistic regression analysis identified it to be an independent risk factor for identifying LNM in GC patients." (PMID 30563560, 2018).
tumor (continued). "Mechanistically, we reveal that the knockdown of antizyme inhibitor 1 (AZIN1) or suppression of polyamine production reduces MYC expression, leading to diminished tumor cell viability via the downregulation of cell cycle-related genes." (PMID 40246846, 2025). "Reducing AZIN1 levels diminished MYC expression and suppressed cell cycle progression, ultimately inhibiting tumor growth." (PMID 40246846, 2025). "Blockade of AZIN1 resulted in a significant delay of tumor progression and prolonged survival, even when using a MYC amplified MB tumor line." (PMID 39962590, 2025). "Tumor identification was facilitated by GFP expression engineered into both the WT and AZIN1 KO D556 cells." (PMID 39962590, 2025). "RNA-edited AZIN1 enhances CRC stemness, promotes tumor angiogenesis, and appears to drive the metastatic processes." (PMID 38169396, 2024). "Previously reported editing events in GRIA2, AZIN1, and COG3 are thought to promote adult tumor progression based on functional cell viability assays." (PMID 34789196, 2021). "Specifically, the serine-to-glycine substitution at residue 367 of AZIN1 was reported in a previous study; the editing may induce a conformational change and a cytoplasmic-to-nuclear translocation, which will result in tumor initiation and aggressive tumor progression." (PMID 32117713, 2020). "Importantly, AZIN1 was also detectable, and significantly higher, in the urine sample of MB patients prior to resection surgery compared to the follow-up sample collected after tumor resection surgery, corroborating our hypothesis that secreted AZIN1 is mainly sourced from the primary MB lesion." (PMID 39962590, 2025). "However, only a few coding RNA editing sites have been characterized, such as AZIN1, GABRA3, FLNB, SLC22A3, and COPA, which can affect tumor progression." (PMID 36895481, 2023). "Although exogenous expression of wild-type (wt) AZIN1 is frequently used as a control for comparison with edAZIN1, wtAZIN1 RNA may be edited by endogenous ADAR1 in tumor cells." (PMID 36202978, 2022). "Our work on the function of RNA-edited AZIN1 in tumor angiogenesis can provide further insights into how A-to-I RNA-edited AZIN1 promotes CRC development and progression and rationales for developing new therapies against tumor angiogenesis." (PMID 35365616, 2022). "While most research on RNA-edited AZIN1 has centered on its role in the tumor rather than the tumor microenvironment, the biological function of RNA-edited AZIN1 on tumor angiogenesis has not been elucidated." (PMID 35365616, 2022). "These variations affected the following genes: AZIN1 (c.A1099G), COG3 (c.A1903G), COPA (c.A490G), GATAD2A (c.A65G), GLT8D1 (c.C955G) and SLC25A39 (c.C809T), and were all verified by Sanger sequencing on tumors and non-tumor DNA." (PMID 33963205, 2021). "Consequently, these data suggest that a dual inhibition strategy in which both AZIN1 and polyamine endocytosis are targeted simultaneously might be a novel approach to be considered in MYC amplified tumor subgroups." (PMID 39962590, 2025). "Stably edited AZIN1 acts as an analog of ornithine decarboxylase (ODC) to prevent the degradation of ODC and cyclin D1, resulting in increased cell proliferation, metastasis potential and tumor initiation in colorectal cancer, esophageal squamous cell carcinoma, and hepatocellular carcinoma." (PMID 36895481, 2023). "High AZIN1 expression was observed in both the benign samples (10/26; 38%) and tumor samples (91/202; 45%), suggesting that overall AZIN1 protein expression may not be a suitable biomarker to differentiate between tumor and benign tissue." (PMID 36202978, 2022). "Third, increased AZIN1 RNA editing and ADAR1 over-expression in GC tissues significantly correlated with key clinico-pathological factors for disease progression, including advanced tumor depth, the presence of lymph node and distant metastases, and higher TNM stages in GC patients." (PMID 30563560, 2018).
adenocarcinoma (1 paper, 2013). A common cancer characterized by the presence of malignant glandular cells. "Of the 152 predicted gene targets in mouse and human genomes, four were significantly regulated in laser dissected lung dysplasia (AZIN1, CHST1, CRISPLD2 and FOXQ1) while 11 genes were significantly regulated in laser-dissected adenocarcinomas." (PMID 24265725, 2013).
bacterial infection (1 paper, 2024). "Additionally, the role of AZIN1 editing may vary depending on the type of injury (e.g., sterile inflammation vs. viral or bacterial infection) and the affected tissues." (PMID 38954486, 2024).
kidney diseases (1 paper, 2024). "As such, AZIN1 A-to-I editing can serve as a molecular clock to stage various forms of kidney disease." (PMID 38954486, 2024). "However, the clinical implications of AZIN1 editing in non-cancerous kidney diseases remain unclear." (PMID 38954486, 2024).
liver (1 paper, 2022). "To conclude, MALAT1 targeted miR-150-5p/AZIN1 to accelerate liver IR injury, suggesting that MALAT1 might be a novel target for liver IR injury." (PMID 36700468, 2022). "More importantly, we conducted rescue experiments and verified that AZIN1 upregulation could neutralize the impacts of MALAT1 silence on the progression of liver IR injury." (PMID 36700468, 2022).
AZIN1 also shares sentences with these, for which no sentence is quoted: non-small cell lung carcinoma (4 papers); liver fibrosis (2); multiple myeloma (2); astrocytoma (1); cervical cancer (1); diabetic kidney disease (1); ependymoma (1); gastric tumor (1); hepatitis C infection (1); leukemia (1); liver cirrhosis (1); lung adenocarcinoma (1); melanoma (1); mucoepidermoid carcinoma (1); neuroblastoma (1); neurological disorders (1); oesophageal cancer (1); oligodendroglioma (1); prostate tumors (1); testicular tumors (1).